USP11 (ubiquitin specific peptidase 11)
Diseases named in the same sentence as USP11 in open-access papers (continued):
Sharing a sentence is not in itself a finding about the gene and the disease.
cervical cancer (4 papers, 2017 to 2025). A primary or metastatic malignant neoplasm involving the cervix. "This study demonstrated that USP11 depletion decreased the proliferation of HPV16+ cervical cancer cells, suggesting that USP11-mediated 16E7 stability is required for its oncogenicity." (PMID 40011575, 2025). "USP11 promotes cervical cancer progression and proliferation through deubiquitination and stabilization of HPV-16E7, subsequently affecting the biological function of E7 as well as the HPV-16E7 contribution to cellular transformation." (PMID 35715413, 2022). "This article merely introduces USP11 into cervical cancer, and the more complicated role and function of USP11 in cervical cancer will be gradually revealed." (PMID 35715413, 2022). "The significant inhibition of cervical cancer proliferation and progression by declining USP11 implies that targeting USP11 is a new and viable therapeutic manner for many cervical cancer patients." (PMID 35715413, 2022). "The relationship between cervical cancer and USP11/NF90 remains to be further investigated." (PMID 35715413, 2022). "We attempted to recapitulate observations shown here in cervical cancer cells (HeLa), and noted that all HeLa cells died when transduced with lentiviral USP11 specific shRNAs, days after the puromycin selection had occurred, suggesting a critical role for USP11 in HeLa cancer cell survival." (PMID 29293652, 2018).
gastric cancer (4 papers, 2022 to 2024). A primary or metastatic malignant neoplasm involving the stomach. "High expression of USP11 was found in gastric cancer patients’ tumor samples, and its upregulation promoted gastric cancer tumor growth and metastasis." (PMID 39048965, 2024). "USP11 enhances the effectiveness of chemotherapy in gastric cancer by RhoA and Ras signaling pathways." (PMID 39605891, 2024). "Targeting USP11 is an excellent strategy for gastric cancer treatment and chemoresistance." (PMID 35715413, 2022).
intracerebral hemorrhage (4 papers, 2021 to 2025). A cerebrovascular disorder characterized by bleeding into one or both cerebral hemispheres including the basal ganglia and the cerebral cortex. "The Usp11 gene, on the other hand, was demonstrated to regulate microglial activation and neuroinflammation in intracerebral hemorrhage (ICH)." (PMID 35203447, 2022). "USP11 promotion of apoptosis has been reported in rat microglia after intracerebral hemorrhage, involving the deubiquitination of substrate protein Beclin 1 by USP11, which is consistent with the role of USP11 in neurological diseases reported in this study USP11." (PMID 39780069, 2025).
lung adenocarcinoma (4 papers, 2016 to 2022). A carcinoma that arises from the lung and is characterized by the presence of malignant glandular epithelial cells. "A549 lung adenocarcinoma cells that stably inhibit USP11 increased colony formation." (PMID 26919101, 2016).
pulmonary fibrosis (4 papers, 2016 to 2025). Chronic progressive interstitial lung disorder characterized by the replacement of the lung tissue by connective tissue, leading to progressive dyspnea, respiratory failure, or right heart failure. "Some investigations have suggested that USP11 is implicated not only in tumorigenesis but also in the progression of pulmonary fibrosis in recent studies." (PMID 38543064, 2024). "Collectively these results demonstrate that MTX treatment, administered preventively or therapeutically, alleviates BLM-induced lung fibrosis by targeting USP11." (PMID 40225577, 2025). "This study provides mechanistic evidence for development of USP11 inhibitors as potential antifibrotic drugs for pulmonary fibrosis." (PMID 27853171, 2016). "Further, we show that both USP11 and TβRII are highly expressed in murine lung tissues from experimental lung fibrosis and IPF patients." (PMID 27853171, 2016). "Here we show that both USP11 and TβRII levels are increased in lung tissues from an experimental lung fibrosis model and IPF patients; however, the molecular regulation of USP11 has not been studied." (PMID 27853171, 2016). "Therefore, we investigated the function of the USP11-mediated SFTPC protein abundance during lung fibrosis." (PMID 40225577, 2025). "Finally, we demonstrated that the pharmacological inhibition of USP11 prevented PF caused by TGF-β in hiPSCs-SFTPCI73T-AOs and bleomycin-induced pulmonary fibrosis (BLM-IPF) mouse model." (PMID 40225577, 2025). "Therefore, we used MTX, a clinically approved and proven USP11 inhibitor 38, to determine the feasibility of targeting USP11 to prevent or treat BLM-induced lung fibrosis in mice." (PMID 40225577, 2025). "As USP11 promotes TGFβ-1 signaling through stabilization of TβRII, we hypothesize that USP11 may have a critical role in the development of lung fibrosis." (PMID 27853171, 2016). "Notably, it has been proposed that targeting the deubiquitinase USP11 may mitigate radiation-induced pulmonary fibrosis by modulating endothelial tight junctions." (PMID 41289299, 2025). "Therefore, USP11 may contribute to the pathogenesis of pulmonary fibrosis by stabilization of TβRII and promotion of TGFβ-1 signaling." (PMID 27853171, 2016). "Taken together, targeting USP11 might be a new strategy to lessen the severity of lung fibrosis." (PMID 27853171, 2016). "Additionally, hiPSCs-SFTPCI73T-AOs treated with TGF-β had a higher collagen gel contraction compared to the wild-type SFTPC, while blocking USP11 with MTX reversed that phenotype, indicating that USP11 inhibition lowers SFTPCI73T-driven pulmonary fibrosis." (PMID 40225577, 2025).
Alzheimer disease (3 papers, 2024 to 2025). A progressive, neurodegenerative disease characterized by loss of function and death of nerve cells in several areas of the brain leading to loss of cognitive function such as memory and language. "USP11 is a promising therapeutic target implicated in Alzheimer’s disease and various cancers; however, no specific inhibitors are currently available, with the only known inhibitor being mitoxantrone, which primarily targets topoisomerase II." (PMID 40588719, 2025).
glioblastoma (3 papers, 2020 to 2025). The most malignant astrocytic tumor (WHO grade IV). "Thus, Notch-induced downregulation of USP11 and PML promotes multiple malignant features of glioblastoma multiforme (GBM) and glioma-initiating cells (GICs), indicating the importance of this pathway in GBM malignancy." (PMID 33158118, 2020).
leukemia (3 papers, 2016 to 2022). A malignant (clonal) hematologic disorder, involving hematopoietic stem cells and characterized by the presence of primitive or atypical myeloid or lymphoid cells in the bone marrow and the blood. "Together, these findings demonstrate that USP11 and USP7 form an oncogenic complex with LCK in leukemia." (PMID 36490346, 2022). "For example, CRL4DCAF8 and USP11 counter-regulate the stability of myeloid leukemia factors (MLFs), and TRIM32/USP11 together balance the stability of ARID1A." (PMID 35359344, 2022). "USP11 ablation inhibits leukemia progression in vivo, sparing normal hematopoiesis." (PMID 36490346, 2022). "In addition to gene mutations that are known to be involved in leukemogenesis, such as ones in MYC and KRAS, we also identified mutations within PTPN21, TBX21, USP54, USP11, NCOR2, CSPP1 that have never before been identified in human leukemia." (PMID 26527318, 2016).
non-small cell lung carcinoma (3 papers, 2019 to 2022). A group of at least three distinct histological types of lung cancer, including non-small cell squamous cell carcinoma, adenocarcinoma, and large cell carcinoma. "Ubquitination is a dynamic and reversible process and NRF2 de-ubiquination was recently reported through the ubiquitin-specific-processing protease 11 (USP11) execution in non-small cell lung cancer cells." (PMID 36358651, 2022). "USP11-mediated deubiquitination of p21 inhibits non-small cell lung cancer growth in vivo." (PMID 31592114, 2019).
pancreatic cancer (3 papers, 2017 to 2024). "Previous researches have proved that USP11 is associated with other gastrointestinal cancers, such as gastric and pancreatic cancer." (PMID 35715413, 2022). "Preliminary analysis indicated that USP11 expression is closely associated with several cancer survival and prognosis, including low-grade glioma (LGG); liver hepatocellular carcinoma (LIHC), pancreatic cancer (PAAD), skin cutaneous melanoma (SKCM), and uveal melanoma (UVM)." (PMID 35715413, 2022). "Prior reports have documented USP11 works in concert with BRCA2 to facilitate DNA homologous recombination by recruiting components of the DNA repair complex, MTX targets USP11 and inhibits pancreatic cancer cell survival." (PMID 39562545, 2024).
renal fibrosis (3 papers, 2023 to 2025). A final common manifestation of a wide variety of chronic kidney diseases characterized by glomerulosclerosis and tubulointerstitial fibrosis. "Studies have shown that an increase in USP11 in pathological states is associated with the promotion of renal fibrosis." (PMID 37196129, 2023). "Patients with renal fibrosis exhibit increased expression of the deubiquitinating enzyme USP11, which positively correlates with the severity of renal fibrosis." (PMID 40225869, 2025). "In the USP11 knockout mouse model of renal fibrosis, the degradation of EGFR was increased, which inhibited downstream signaling pathways and delayed the renal fibrosis and epithelial-mesenchymal transition." (PMID 40225869, 2025). "USP11 phosphorylates TβRΙ by deubiquitinating TβRII and reducing TβRII ubiquitination degradation, which then activates the downstream Smad2/3 or nonclassical pathway to promote the activation of downstream senescence signalling pathways and the development of renal fibrosis." (PMID 37196129, 2023).
spinal cord ischemia (3 papers, 2024 to 2025). Reduced blood flow to the spinal cord which is supplied by the anterior spinal artery and the paired posterior spinal arteries. "Moreover, it has been shown that the expression of USP11 is increased in neuronal cellular ferroptosis, and USP11 regulates autophagy-dependent ferroptosis after spinal cord ischemia/reperfusion injury through the deubiquitination of Beclin1,109 which limits recovery from this disease." (PMID 40083330, 2025).
breast neoplasm (2 papers, 2023 to 2024). A benign or malignant neoplasm of the breast parenchyma. "A microarray database, which was published earlier, has demonstrated the expression of USP11 in human prostate and breast neoplasms." (PMID 38139829, 2023). "In human breast tumor samples, the mRNA expression of USP11 in ER- and PR-double-negative (ER-/PR-) tumors was significantly lower than that in ER- and PR-double-positive (ER+/PR+) tumors, showing a decreased expression of USP11 in advanced breast tumors." (PMID 39270819, 2024).
Cognitive impairment (2 papers, 2024 to 2026). Abnormal cognition is characterized by deficits in thinking, reasoning, or remembering. "This approach could alleviate cognitive impairments in dementia mouse models, suggesting that effective suppression of USP11 function by inhibitors could provide a potential therapeutic strategy for AD." (PMID 39394468, 2024). "Furthermore, we generated astrocyte‐specific Usp11 knockout (Usp11CKO) mice and found that astrocyte‐specific Usp11 knockout similarly demonstrated significant reductions in brain water content, alleviation of sensorimotor deficits, and mitigation of cognitive impairments post‐ICH." (PMID 41201111, 2026).
depression (2 papers, 2020 to 2026). "The interaction protein CK2α of USP11 in depression was identified by IP-MS, and the role of CK2α was confirmed by using the selective inhibitor CX4945." (PMID 42231570, 2026).
liver disease (2 papers, 2021 to 2022). "They further found that USP11 was negatively related to different liver diseases, such as fatty liver and non-alcoholic fatty liver disease." (PMID 35715413, 2022). "Our functional results provide evidence for the crosstalk between KLF4 and USP11 in hepatic diseases; in particular, they show how USP11 enhances HCC tumorigenesis and steatosis through KLF4 inhibition." (PMID 34114341, 2021). "These evidences further identify the critical role of USP11/KLF4 axis in the occurrence and development of different liver diseases, which might be a potential target for the treatment of various liver-origin diseases." (PMID 35715413, 2022). "Collectively, these findings suggest that USP11, as KLF4‐binding partner, is an important mediator of hepatic tumorigenesis that functions via degradation of KLF4 and is a potential treatment target for liver diseases." (PMID 34114341, 2021). "Since USP11 has been previously reported as an oncogene in HCC, but its underlying molecular mechanisms in hepatic disease are not entirely understood, we decided to further explore its activity as KLF4‐binding partner." (PMID 34114341, 2021). "More importantly, we demonstrated the negative correlation between KLF4 and USP11 expression in liver diseases such as non‐alcoholic fatty liver disease (NAFLD) and HCC." (PMID 34114341, 2021).
lymphoma (2 papers, 2022 to 2025). A malignant (clonal) proliferation of B- lymphocytes or T- lymphocytes which involves the lymph nodes, bone marrow and/or extranodal sites. "Furthermore, utilizing the GDS2554 database, we found that the expression of Usp11 in B cells derived from aggressive lymphoma samples was significantly reduced compared to that in normal resting B cells." (PMID 39904982, 2025). "USP11 deubiquitinates and stabilizes the translation initiation factor EIF4B to promote EIF4B-dependent oncogenic translation, thus phosphorylating USP11 enhances the stability and abundance of EIF4B, which ultimately facilitates the occurrence of lymphoma." (PMID 35715413, 2022). "The GDS2762 database was analyzed to compare the expression of Usp11 in B cells stimulated by IFN-β and in B cells that were not stimulated, and the GDS2554 database was analyzed to compare the expression of Usp11 in normal resting B cells and aggressive lymphoma sample B cells." (PMID 39904982, 2025).
prostate tumors (2 papers, 2019 to 2023). "Interestingly, a recent transcriptome profiling analysis of human prostate cancer revealed that USP11 transcript expression was downregulated in primary prostate tumors, and its reduction was closely associated with tumor aggressiveness." (PMID 30733438, 2019). "In comparison with samples derived from prostate tumors, those obtained from neighboring benign tissues had higher levels of USP11 (p < 0.04)." (PMID 38139829, 2023). "As decreasing PTEN levels correlate with increased initiation and progression of prostate tumors in the mouse, we assessed the role of USP11 in prostate tumorigenesis in vivo." (PMID 30733438, 2019). "Notably, an immunohistochemical analysis of human prostate tumors demonstrated a statistically significant positive correlation (r = 0.385, p = 0.012) between USP11 and PTEN protein levels, as 72.9% (35 of 48) of the tumors with low USP11 expression also exhibited low PTEN expression." (PMID 30733438, 2019).
skin cancer (2 papers, 2017 to 2022). "We found that human and mouse skin tumors associated with UV damage show down-regulation of USP11, suggesting that USP11 acts as a tumor suppressor in skin cancer." (PMID 29228550, 2017). "Since CPD, and not 6-4PP, is responsible for UV-induced skin carcinogenesis, the positive regulation of CPD repair by USP11 suggests a tumor suppressor role of USP11 in skin cancer." (PMID 29228550, 2017). "Our findings demonstrate a crucial role of USP11 in UV-induced DNA damage repair and suggest USP11 as a tumor suppressor in skin cancer." (PMID 29228550, 2017). "Our results indicate that USP11 positively regulates repair of UV-induced CPD DNA damage, and suggests a tumor suppressive function of USP11 in skin cancer." (PMID 29228550, 2017). "The function of USP11 in promoting the NER process further supports the tumor suppressive role of USP11 in skin cancer." (PMID 29228550, 2017). "To determine the regulation of USP11 by UV exposure and in UV-induced skin cancer, we evaluated the protein levels of USP11 by immunohistochemical staining in skin tissue from sham-irradiated and chronic UVB-irradiated mice (n = 9)." (PMID 29228550, 2017). "Consequently, USP11 inhibitors like mitoxantrone, and more specific USP11 inhibitors developed in the future, have the potential for cancer therapy in skin cancer and other cancers with NER involvement." (PMID 29228550, 2017). "Furthermore, we found that USP11 is down-regulated in chronically UV-exposed mouse skin and in skin tumors from mice and humans." (PMID 29228550, 2017). "The contradictory role of USP11 in skin tumors might be a disturbing consequence of DNA damage." (PMID 35715413, 2022). "However, the significance of USP11 in skin cancer is unknown." (PMID 29228550, 2017). "Our data indicate that USP11 is a positive regulator for NER, and suggest that USP11 acts as a tumor suppressor in UV-induced skin cancer." (PMID 29228550, 2017). "USP11 is down-regulated in mouse skin with chronic UVB irradiation and skin tumors from mice and humans." (PMID 29228550, 2017). "We further determined whether the mechanism of USP11 activity was via regulating deubiquitination of XPC, as well as USP11’s role in skin cancer." (PMID 29228550, 2017). "These insights into the mechanism of USP11 action on XPC deubiquitination and NER suggest that USP11 could be a promising target for treatment of skin cancer." (PMID 29228550, 2017). "Furthermore, USP11 is down-regulated in mouse skin with chronic UVB irradiation and skin tumors from mice and humans." (PMID 29228550, 2017).
T-cell leukemia (2 papers, 2022 to 2024). A malignant disease of the T-lymphocytes in the bone marrow, thymus, and/or blood. "In this study, we have demonstrated a previously unidentified role for the deubiquitinase complex of USP7 and USP11 in regulating LCK kinase signaling and therapy response in T cell leukemia." (PMID 36490346, 2022). "Usp11 knockout animals are viable, suggesting that USP11 is not required for organismal homeostasis and that targeting USP11 might be a therapeutic modality in T cell leukemia." (PMID 36490346, 2022).
tauopathies (2 papers, 2024). "Moreover, X-linked ubiquitin-specific peptidase 11 (USP11) has been shown to increase susceptibility to tauopathy in women." (PMID 38930877, 2024). "In a mouse model of tauopathy, elimination of the USP11 gene preferentially protects females against acetylated tau accumulation, tau pathology, and cognitive impairment." (PMID 38930877, 2024). "USP11 levels in females are also strongly associated with tau pathology, and the inhibition of USP11-mediated deubiquitination of tau protein may provide an effective therapeutic approach to protect females from increased susceptibility to AD and other tauopathies." (PMID 38930877, 2024). "Genetic elimination of USP11 in a tauopathy mouse model showed preferential protection in females against acetylated tau accumulation, tau pathology, and cognitive impairment." (PMID 39562545, 2024).